INS (insulin)
Diseases named in the same sentence as INS in open-access papers (continued):
Sharing a sentence is not in itself a finding about the gene and the disease.
Hypoglycemia (continued). "The APX ratswhen compared to normals had a greater sensitivityto insulin-induced hypoglycemia while IGF-1 decreasedthe plasma glucose to a lesser degree in APXrats." (PMID 11469391, 2000). "The actions of insulin and glucagon must be finely balanced, because both lower than normal blood sugar levels (i.e., hypoglycemia) and higher than normal blood sugar levels (i.e., hyperglycemia) can have deleterious effects on the body." (PMID 15706798, 1998). "If insulinomas overexpress GIP and GLP receptors, use of tirzepatide could intensify postprandial insulin production and provoke severe postprandial hypoglycemia." (PMID 41356535, 2026). "In T1D, where exogenous insulin is required, protein’s glucagon-stimulating properties can be leveraged to prevent delayed or overnight hypoglycemia, assist during prolonged activity, or enhance mild hypoglycemia treatment." (PMID 41602572, 2026). "While longer durations of activity may further reduce glucose, they also increase the likelihood of hypoglycaemia, particularly when insulin on board is present." (PMID 41194332, 2026). "Despite a modest reduction in receptor potency relative to native dasiglucagon, this approach provides significant prophylactic protection in a streptozotocin-induced diabetic mouse model of insulin overdose, rescuing mice from hypoglycemia and eliminating mortality events." (PMID 41810046, 2026). "While one of the goals of this study was to assess the possible effect of SSTR2 antagonism on the efficacy of bolus insulin to restore euglycemia, the dose given may have been too high as some of the animals developed hypoglycemia in both treatment groups." (PMID 41502124, 2026). "A diagnosis of DM and ongoing contact with healthcare services may lead to behavioral changes aimed at reducing alcohol intake, particularly due to concerns about hypoglycemia, especially among individuals treated with insulin or sulfonylureas." (PMID 41562684, 2026). "Sustained insulin secretory capacity, defined in the DCCT by a stimulated C-peptide >200 pmol/l at baseline and at least 1 year later, is also associated with lower rates of hypoglycaemia in those treated with intensive insulin therapy." (PMID 41355468, 2026). "In our model, basal insulin replacement was provided by subcutaneous insulin implants (LinBit), which we have shown previously are sufficient to prevent metabolic decompensation, while recurrent hypoglycaemia was induced at planned intervals with rapid-acting insulin." (PMID 41212210, 2026). "The models themselves pursue five practical outputs that map neatly onto the clinical pathway: (i) near-term glucose forecasting (nocturnal hypoglycemia, post-prandial spikes), (ii) automated, individualized insulin dosing via closed-loop/artificial-pancreas systems." (PMID 41596449, 2026). "The early-morning fasting hypoglycemia observed during CGM after admission was considered to be influenced by several factors: delayed insulin clearance because of impaired renal function, reduced hepatic glucose production related to cirrhosis, and improved insulin sensitivity." (PMID 41536580, 2026). "Furthermore, 37% (n = 185) limited their driving due to insulin-related concerns, and 72% (n = 359) worried particularly about hypoglycemia." (PMID 42218605, 2026). "However, insulin overdosing in some type 1 diabetic patients, who are physically active, can lead to unexpected hypoglycemia beyond the control of the common artificial pancreas." (PMID 41766716, 2026). "For individuals treated with insulin, hypoglycemia represents the principal safety concern." (PMID 42218605, 2026). "While intravenous glucose is typically used only for severe or nocturnal hypoglycemia, pharmacologic therapy may employ somatostatin analogues or diazoxide in certain situations to reduce insulin secretion." (PMID 41589093, 2026).
Hypoglycemia (continued). "The primary endpoint was change in HbA1c; secondary endpoints included insulin dose(U/kg), hypoglycemia frequency, 3:00 a.m. glucose, lipid parameters, body composition, Numeric Rating Scale (NRS) for pain, and Pediatric Quality of Life Inventory (PedsQL) scores." (PMID 41998571, 2026). "Nesidioblastosis has been hypothesized to develop from increased secretion of gastrointestinal hormones, such as GLP-1, stimulating β-cell growth and eventually contributing to hypoglycemia by exaggerated insulin release." (PMID 40799776, 2025). "Serum collected at presentation was submitted post-mortem for an insulin level which was found to be discordantly elevated, which may demonstrate an alternative mechanism of hypoglycemia in this case." (PMID 40607356, 2025). "Therefore, the paracrine regulatory mechanism of somatostatin facilitates the timely reduction in peripheral insulin levels once peripheral blood glucose concentrations normalize, thereby preventing the onset of hypoglycemia." (PMID 40919135, 2025). "However, excessive insulin administration can induce hypoglycemia, a life‐threatening condition characterized by abnormally low blood glucose levels." (PMID 39887601, 2025). "A critical sample collected during hypoglycemia demonstrated elevated insulin levels (up to 62 μIU/mL, normal range: 2.6-24.9 μIU/mL) and C-peptide concentrations (3.1 nmol/L, normal range: 0.37-1.47 nmol/L), with suppressed ketone levels (0.1 mmol/L, normal range: 0.0-0.6 mmol/L)." (PMID 41531556, 2025). "Moreover, by administering glucose during the test, we prevented the severe hypoglycemia often induced in highly insulin-sensitive animals during the conventional ITT." (PMID 39872987, 2025). "Their potency appears to increase with higher baseline HbA1c levels, and in patients with lower baseline HbA1c, GLP-1 RAs may outperform basal insulin—possibly due to suboptimal insulin titration driven by concerns over hypoglycemia." (PMID 40870388, 2025). "Insulin-induced hypoglycemia may also contribute to this process by stimulating epinephrine secretion." (PMID 41149081, 2025). "Unlike other antidiabetic medications, metformin does not stimulate insulin secretion, which significantly reduces the risk of hypoglycemia, making it safer for long-term use." (PMID 39958117, 2025). "Their action is independent of insulin, hence they reduce blood glucose concentrations without causing hypoglycaemia." (PMID 40651878, 2025). "This overlap suggests that insulin and glucose dynamics, a common feature in idiopathic postprandial hypoglycemia, may play a role in PPH as well." (PMID 39940337, 2025). "Compared to human insulin, IG has a slower onset but a significantly longer duration of action, contributing to its once-daily dosing and flatter pharmacokinetic profile, which helps improve postprandial blood glucose control and reduce nighttime hypoglycemia." (PMID 40997126, 2025). "We further examined the effects of the first-phase insulin secretion on hypoglycemia." (PMID 41433229, 2025). "Considering the severe hypoglycemia episodes even after insulin discontinuation, the hypothesis of new-onset hyperinsulinemia was considered and bloodwork was performed, confirming inappropriate hormonal production." (PMID 41561059, 2025). "Diagnosis is based on elevated insulin levels and, on the other most common symptom, hypoglycemia." (PMID 40291307, 2025). "The potential benefits are significant: Due to exquisite functional precision, minimal endogenous beta cell capacity can reduce severe hypoglycemia associated with exogenous insulin therapy even if insulin independence is not achieved." (PMID 41289263, 2025). "The second type is non-IAA autoantibodies which, if fortuitously/incidentally present in patients with hypoglycaemia, could interfere with insulin and/or C-peptide immunoassay measurements, also confusing differential diagnosis." (PMID 41349642, 2025).
Hypoglycemia (continued). "This implies that social isolation in female rats may lead to dysfunction in the central insulin signaling that can facilitate a recovery of blood glucose levels following hypoglycemia." (PMID 39821966, 2025). "Conversely, the presence of high levels of insulin, due to exogenous insulin administration, could attenuate or even prevent the increased mobilization of glucose and other substrates induced by exercise, and hypoglycemia might ensue." (PMID 40407447, 2025). "In this case, even a slightly higher dose of insulin than needed may lead to the development of hypoglycemia, while a slightly lower than needed insulin dose leads to increases in BG levels." (PMID 40136987, 2025). "In addition, the study will investigate the safety profile (in particular, hypoglycemia and immunosuppressive drugs levels) and the effect of semaglutide on graft function, weight, and daily insulin dose." (PMID 40649730, 2025). "Hypoglycemia occurs if too much insulin is administered relative to the turnover of carbohydrates." (PMID 41212850, 2025). "However, in terms of pregnancy outcomes, CSII use was associated with statistically significant increases in the risk of cesarean delivery, neonatal hypoglycemia, LGA newborns, and lower insulin doses." (PMID 41467142, 2025). "For these patients, DPP-4 inhibitors remain a cornerstone therapy, as they effectively enhance insulin secretion without increasing the risk of hypoglycemia." (PMID 40607140, 2025). "Issues such as fear of hypoglycemia, difficulty with self‐monitoring of blood glucose and inadequate support systems may result in suboptimal insulin use, thereby contributing to poor glycemic control." (PMID 40078898, 2025). "Consequently, insulin treatment continues during this period, and IV glucose is commonly required to prevent hypoglycemia while insulin administration is in progress, to arrest ketogenesis and reverse metabolic acidosis." (PMID 41227190, 2025). "Patients of this type may experience intermittent hypoglycaemia because they are insensitive to the effects of insulin injection therapy." (PMID 40950999, 2025). "For example, insulin-sensitive animals with lower fasting blood glucose levels will undergo hypoglycemia which will elicit a counterregulatory survival response that may lead to an underestimation of insulin sensitivity." (PMID 39872987, 2025). "This marked insulin secretion leads to the hypoglycemia observed in these patients." (PMID 41194783, 2025). "Individuals with DM may experience complications, including peripheral neuropathy, vestibular dysfunction, cognitive impairment, musculoskeletal or neuromuscular problems in the lower limbs, dizziness, and hypoglycemia, specifically with insulin use." (PMID 40991555, 2025). "A plausible explanation lies in its flat and sustained exposure profile, which may reduce glycemic variability, hypoglycemia, and the subsequent defensive caloric intake that often drives weight gain with conventional insulin regimens." (PMID 41152194, 2025). "An insulin infusion was deferred to avoid recurrent severe hypoglycemia." (PMID 41146800, 2025). "For patients on insulin therapy, precise carbohydrate management, including carbohydrate counting and prioritizing low-GI foods, ensures accurate dosing and minimizes the risks of hypoglycemia and hyperglycemia." (PMID 39859337, 2025). "Within the context of hypoglycaemia, this pattern indicates that the hypoglycaemia is not caused by insulin overproduction or exogenous insulin administration but rather by an insulin-like substance." (PMID 41329563, 2025). "A 72-year-old Saudi male with T1DM, first diagnosed at the age of 14 years, was transitioned to insulin pump therapy due to persistent glycemic variability, frequent hypoglycemia (three to four episodes per week), and hypoglycemia unawareness while on multiple daily insulin injections (MDIs)." (PMID 41473654, 2025).
Hypoglycemia (continued). "In one published by Chen and colleagues, sunitinib stabilized tumor growth after two years of treatment but was noted to worsen hypoglycemia, an effect attributed to the drug’s ability to enhance glucose-dependent insulin secretion and reduce insulin clearance." (PMID 40648766, 2025). "However, evidence regarding treatment satisfaction, total daily insulin dose, and hypoglycemia remains inconclusive." (PMID 39965802, 2025). "The relatively new antidiabetic drug class glucagon-like peptide 1 receptor agonists (GLP-1 RAs) stimulate β-cells to secrete more insulin without causing hypoglycemia." (PMID 40760325, 2025). "This is partially because of the appetite-suppressing effects of liraglutide leading to lower food intake, potentially increasing the risk of hypoglycemia, especially when insulin doses are not properly down titrated." (PMID 40707821, 2025). "This indicates that ICU nurses have a good grasp of the knowledge of insulin use and hypoglycemia management, which may be related to the fact that these contents are more common and operable in daily work." (PMID 41366921, 2025). "The most common adverse effect of insulin and its analogues is hypoglycemia." (PMID 40574081, 2025). "Hypoglycemia is more commonly observed in patients with type 1 diabetes (T1DM) compared to type 2 diabetes (T2DM), as individuals with T1DM are typically dependent on insulin or insulin secretagogues, which increase the risk of low blood glucose levels." (PMID 40585626, 2025). "Compared to empirically managed continuous intravenous insulin infusion, the IP resulted in better average blood glucose levels while reducing the burden of blood glucose measurements and insulin adjustment, without increasing the risk of hypoglycemia." (PMID 40400655, 2025). "Additionally, the inclusion of D5W in fluids helps prevent hypoglycemia by providing an exogenous glucose source while insulin is being used." (PMID 40725973, 2025). "Daily insulin injections, glucose level checks, experiencing hypoglycemia may contribute to the feelings of isolation and disease-related stigma experienced by individuals with T1D during adolescence that can carry over into adulthood." (PMID 41480084, 2025). "Lower peripheral insulin levels may also help preserve glucagon response and hepatic glucose production during hypoglycemia or exercise." (PMID 40995084, 2025). "Most of the nurses can perform blood glucose management measures well in practice; for example, 85.81% of the nurses will judge the insulin sensitivity of the patients when giving insulin treatment, and 85.48% of the nurses will remeasure blood glucose 15 to 30 minutes after hypoglycemia treatment." (PMID 41366921, 2025). "Thus, novel tools to guide targeted treatment in the early phase of ICU or CCU admission are needed to improve outcomes, such as machine learning for hypoglycemia prediction and close loop insulin delivery systems." (PMID 40150028, 2025). "Results from our pilot study demonstrate that a low-carbohydrate diet significantly reduced glycemic variability and insulin requirements without increasing the risk of hypoglycemia or ketoacidosis in patients with insulin-deficient diabetes." (PMID 41586239, 2025). "Patients with active lifestyles may need lower insulin doses or adjustments in timing to prevent hypoglycemia during and after physical activity." (PMID 40190894, 2025). "DRL insulin bolus adviser improved percentage time in target scope (70-180 mg/dL) from 74.1% to 80.9% (for adults) and 54.9%-61.6% (for adolescents) while reducing hypoglycemia." (PMID 40198108, 2025). "In the NICE-SUGAR study, the presence of severe hypoglycemia doubled the risk of mortality, with the effect being most pronounced (3.8-fold increase in risk) among patients who were not receiving insulin therapy." (PMID 41464722, 2025). "Following administration of insulin for HK, hypoglycemia may occur in up to 75% of patients, and tachycardia is common following albuterol administration." (PMID 41178555, 2025).
Hypoglycemia (continued). "Medication adherence also remains suboptimal (53% for α-glucosidase inhibitors, 55% for biguanides, 61% for Sodium-Glucose Cotransporter 2 Enzyme Inhibitors and insulin secretagogues), often due to side effects such as hypoglycemia and gastrointestinal discomfort." (PMID 40725154, 2025). "Based on reports of hypoglycemia-mediated organ regulation via protein phosphorylation, this study characterized hepatic and pancreatic phospho-signaling dynamics in response to insulin overdose." (PMID 41303503, 2025). "However, the occurrence of hypoglycemia in some patients post-insulin discontinuation highlights the necessity for vigilant glucose monitoring and patient education regarding hypoglycemia recognition and management." (PMID 41332894, 2025). "A critical safety consideration in insulin gene therapy is preventing potentially dangerous insulin overexpression, which could lead to life-threatening hypoglycemia." (PMID 40869431, 2025). "However, older adults with higher care needs remain more vulnerable to hypoglycemia, likely due to greater frailty and higher insulin use." (PMID 40777704, 2025). "Hypoglycemia resulting from insulin use was the most commonly identified ADR in the ICUs studied." (PMID 40463907, 2025). "Although PPH and idiopathic postprandial hypoglycemia are distinct conditions, both are postprandial phenomena that may share overlapping mechanisms, including exaggerated insulin response and impaired autonomic regulation." (PMID 39940337, 2025). "However, the traditional subcutaneous (SC) mode of insulin delivery has several limitations, including the intricacy of insulin regimens, potential for hypoglycemia, adverse consequences of weight gain, and requirement for needle puncture." (PMID 39815320, 2025). "Additionally, insulin therapy is believed to be associated with increased risk of ASCVD and hypoglycemia." (PMID 40861717, 2025). "Although NICTH is typically diagnosed with an IGF-2/IGF-1 ratio greater than 10, a ratio below this threshold does not exclude the diagnosis, particularly in the presence of fasting hypoglycemia with suppressed insulin and ketones, findings consistent with IGF-2 mediated effects." (PMID 40727482, 2025). "Additionally, we examine in detail the findings of clinical trials evaluating the efficacy and safety of intensive insulin treatment for hyperglycemic patients in intensive care units, alongside the potential risks of hypoglycemia and mortality." (PMID 39679824, 2025). "If Whipple’s triad has been confirmed, the differential diagnosis for hypoglycemia is broad and can be classified into two categories to assist with diagnostic accuracy and management: non-insulin-mediated hypoglycemia and insulin-mediated hypoglycemia." (PMID 40648766, 2025). "Our findings provide robust real‐world evidence that short bouts of PA, when used alongside insulin therapy, can rapidly lower glucose by ~2.0 mmol/L within 20 min, without increasing immediate hypoglycaemia risk." (PMID 41059660, 2025). "As demonstrated in isolated rat islets, and later confirmed in human studies [103,], GIP has negligible effects on insulin secretion under conditions of hypoglycemia, but strongly potentiates insulin secretion when circulating glucose levels reach or exceed 6–8 mmol/l." (PMID 40024571, 2025). "If needed to achieve glycemic goals, use of anti-diabetic agents showing potential CV benefits (e.g., metformin, pioglitazone) or proven CV safety (e.g., DPP-4 inhibitors, lixisenatide, exenatide, insulin, glimepiride) with lower risks of hypoglycemia is recommended." (PMID 41299307, 2025). "Such insights will be critical for developing targeted interventions to preserve brain integrity in individuals exposed to recurrent or sustained hypoglycemia, whether through insulin therapy, strict CR, or intermittent fasting." (PMID 41408035, 2025).